GLMP (glycosylated lysosomal membrane protein)
Description:
Required to protect lysosomal transporter MFSD1 from lysosomal proteolysis and for MFSD1 lysosomal localization.
Synonyms: C1orf85; MGC31963; NCU-G1; lnc-UCID
Tractability: Antibody: UniProt predicts a signal peptide or a membrane-spanning region. PROTAC: ubiquitination databases record sites on it.
Gene: Protein-coding gene on chromosome 1 (156,290,089 to 156,295,689, reverse strand). Ensembl gene ENSG00000198715.
Subcellular location: Lysosome membrane
Gene Ontology:
Biological process: positive regulation of transcription by RNA polymerase II; protein localization to lysosome; protein stabilization
Cellular component: cytosol; lysosome; nucleus; membrane; lysosomal membrane
Genetic constraint (gnomAD): Loss-of-function variants: 37 observed, 38.51 expected, observed/expected ratio (o/e) 0.96, 90% interval 0.74 to 1.26. The upper end of that interval is the gene's LOEUF score, 1.26, which puts it in group 5 of 6, group 1 being the genes least tolerant of losing a copy. Missense variants: 454 observed, 509.97 expected, observed/expected ratio (o/e) 0.89, 90% interval 0.82 to 0.96. Synonymous variants: 220 observed, 220.13 expected, observed/expected ratio (o/e) 1, 90% interval 0.89 to 1.12.
Homologues: Orthologues: chimpanzee GLMP (99% identical), rabbit GLMP (83% identical), pig GLMP (83% identical), guinea pig GLMP (80% identical), dog GLMP (79% identical), mouse Glmp (78% identical), rat Glmp (78% identical), macaque GLMP (63% identical), tropical clawed frog glmp (42% identical), zebrafish glmp (33% identical).
Diseases named in the same sentence as GLMP in open-access papers:
GLMP is named in the same sentence as 14 diseases in open-access papers, as found by Europe PMC text mining. Sharing a sentence is not in itself a finding about the gene and the disease. The quoted sentences say what the papers report.
liver fibrosis (4 papers, 2014 to 2023). "Using the Glmpgt/gt mouse, a mouse model lacking this lysosomal membrane protein, and characterized by chronic liver injury and liver fibrosis, we assessed the metabolic consequences of GLMP ablation, focusing on liver." (PMID 26047317, 2015). "Ablation of glycosylated lysosomal membrane protein (GLMP, formerly known as NCU-G1) has been shown to cause chronic liver injury which progresses into liver fibrosis in mice." (PMID 26047317, 2015). "Importantly, we found that a subset of those proteins, CTSB, LIPA, DPP7, and GLMP had been previously connected with liver fibrosis, liver damage, and steatosis." (PMID 34440927, 2021). "Importantly, we found that lysosomal DEPs, including CTSB/D/Z, LIPA, DPP7 and GLMP, and mitocondrial DEPs, AKR1B10, and VAT1 had been connected with liver fibrosis, damage, and steatosis in previous studies, validiting our dataset." (PMID 34440927, 2021). "The Glmpgt/gt mouse lacks expression of a subunit of the MFSD1/GLMP lysosomal membrane protein transporter complex, is born normal, but soon develops chronic, mild hepatocyte injury, leading to slowly progressing periportal liver fibrosis, and splenomegaly." (PMID 37910485, 2023). "Interestingly, lysosomal proteins such as cathepsin B (CTSB), lysosomal acid lipase (LIPA), dipeptidyl peptidase 2 (DPP), and glycosylated lysosomal membrane protein (GLMP), which are known to be involved in liver fibrosis, liver damage, and steatosis, were found to be differentially expressed." (PMID 34440927, 2021).
head and neck squamous cell carcinoma (3 papers, 2023 to 2025). A squamous cell carcinoma that arises from any of the following anatomic sites: lip and oral cavity, nasal cavity, paranasal sinuses, pharynx, larynx, and salivary glands. "Furthermore, in head and neck squamous cell carcinoma (HNSCC), NAT10-mediated ac4C modification of glycosylated lysosomal membrane protein (GLMP) mRNA activates the MAPK/ERK signaling pathway, leading to the promotion of lymph node metastasis." (PMID 41316475, 2025).
hemangioma (1 paper, 2021). A benign vascular lesion characterized by the formation of capillary-sized or cavernous vascular channels. "The full knockout of GLMP leads to liver fibrosis with inflammation, oval cell activation, and proliferation, hepatocyte apoptosis, oxidative stress, and development of HCC and hemangioma-like tumors from the age of 12 months." (PMID 33467660, 2021).
liver disease (1 paper, 2020). "MFSD1 has been found to be tightly connected to Glycosylated Lysosomal Membrane Protein (GLMP) where the loss of MFSD1 causes severe liver disease in MFSD1-knockout mice." (PMID 32733888, 2020).
tongue cancer (1 paper, 2023). A malignant neoplasm affecting the tongue. "Specimens of normal, tongue hyperplasia, and tongue carcinoma mice after 4-NQO withdrawal were obtained to detect the expression levels of NAT10 and GLMP using HE staining and western blotting." (PMID 37914704, 2023).
cancer (2 papers, 2023 to 2024). A tumor composed of atypical neoplastic, often pleomorphic cells that invade other tissues. "The results showed that NAT10 and GLMP expression levels increased in normal, hyperplastic, and carcinoma tissues." (PMID 37914704, 2023). "However, the role of GLMP in cancer remains still largely unknown." (PMID 37914704, 2023). "Notably, the levels of expression of these genes, added to six other genes involved in mitochondria activity (TST, NSUN3, GLMP and PTCD2), were reduced following the expression of HLA-G in the RCC7 cells, consistent with mitochondrial impairment found in many types of cancer, particularly in ccRCC." (PMID 39358558, 2024).
tumor (2 papers, 2022 to 2023). "RNA-seq of TCGA-HNSCC data showed that GLMP expression was elevated in HNSCC tumor tissues." (PMID 37914704, 2023). "In tumor cells, the strongest MFSD1 staining co-localized with its accessory subunit GLMP in the Golgi apparatus." (PMID 35211397, 2022). "UALCAN portal analysis of GLMP expression in HNSCC based on nodal metastasis indicated that GLMP expression was significantly higher in HNSCC tissues with N0, N1, N2, and N3 LN metastases than in normal tissues, as well as in advanced tumor stages and grades." (PMID 37914704, 2023).
GLMP also shares sentences with these, for which no sentence is quoted: chronic obstructive pulmonary disease (1 paper); hepatocellular carcinoma (1); lysosomal disorders (1); Paget disease (1); prostate carcinoma (1); Splenomegaly (1); steatosis (1).